IGF1 (insulin like growth factor 1)
Diseases named in the same sentence as IGF1 in open-access papers (continued):
Sharing a sentence is not in itself a finding about the gene and the disease.
liver fibrosis (continued). "As compared with individuals at low probability of liver fibrosis, individuals at high probability of fibrosis exhibited a worse cardio-metabolic risk profile having significantly higher values of waist circumference, hsCRP, fibrinogen, ESR as well as lower levels of HDL, and IGF-1." (PMID 25111713, 2014). "Regarding treatment, favorable effects of recombinant GH (rhGH) on hepatic steatosis and, possibly, on hepatic fibrosis progression in patients with MASLD and GHD or with low IGF-1 concentrations have been demonstrated in interventional studies." (PMID 41708551, 2026). "A mouse model of inflammatory cholestasis and hepatic fibrosis in Ghr-knockout mice crossed with multidrug resistance gene 2-knockout mice exhibit downregulated HNF6, IGF-1, and STAT5 expression levels." (PMID 39910442, 2025). "While these investigations established RNF41’s role in hepatic fibrosis through mechanisms involving macrophage phenotype switching via the C/EBP-β/PPAR-γ pathway and subsequent IGF-1-mediated HSC inactivation, they were limited to liver tissue analyses." (PMID 40861243, 2025). "A pilot study found that there was a close relationship between serum IGF-1 and IGFBP-1 levels and advancement of liver fibrosis of NAFLD." (PMID 38041076, 2023). "Three-dimensional- (3D-) cultured ADMSCs, which produced high levels of HGF, IGF-1, SDF-1, and other proteins, showed a protective effect on liver fibrosis." (PMID 36248254, 2022). "However, the indepth mechanism about ameliorating liver fibrosis with IGF-1 is unknown yet." (PMID 31171766, 2019). "Other top-scored pathways included hepatic fibrosis/HSC activation, ErB signaling, IGF1 signaling and GH signaling." (PMID 29538454, 2018). "External administration of IGF-1 reduced serum ALT and AST levels, severity of liver fibrosis, LPS levels in portal vein, enterocytic apoptosis and portal pressure in cirrhotic rats." (PMID 26152281, 2015). "Thus, MMP-19-deficiency improves the development of hepatic fibrosis through the diminished replacement of physiological extracellular matrix with fibrotic deposits in the beginning of the injury, leading to subsequent changes in TGF-ß and IGF-1 signaling pathways." (PMID 23056273, 2012). "IGF-1 was secreted primarily by the liver and was decreased in patients with NAFLD, which could play a protective role in the liver fibrosis process." (PMID 39227971, 2024). "Recent reports suggest that IGF-1 biodisponibility might be decreased during disease progression toward NASH and liver fibrosis and advance IGF-1/intact IGFBP3 ratio as a fibrosis predictor." (PMID 34249975, 2021). "The previous reports showed that activation of insulin-like growth factor-1 (IGF-1) signaling could enhance cell longevity and attenuate liver fibrosis." (PMID 31171766, 2019). "IGF-1 expression levels in both serum and liver tissue are not correlated to liver fibrosis progression in NASH patients." (PMID 27135827, 2016). "After hanging drop culture for 1, 2, and 3 days, RT-PCR was used to determine the expression levels of cytokines, including insulin growth factor 1 (IGF-1), interleukin-6 (IL-6), and hepatocyte growth factor (HGF), which play important roles during inhibition of hepatic fibrosis." (PMID 27022400, 2016). "As IGFBP5 impairs the binding of IGF1 to the cell-surface receptor IGF1R, its increased expression in activated HSC and myofibroblasts may reduce IGF1 signalling and, thus, promote liver fibrosis." (PMID 20163708, 2010). "Unfortunately, neither measuring liver enzymes nor IGF-1 can determinate the extent of hepatic fibrosis progression in BMT patients and different outcomes of liver disease may be expected in these patients." (PMID 24803998, 2014). "Despite a normal Igf1 response to GH during BDL, GH does not improve hepatic fibrosis in KO mice." (PMID 27936029, 2016).
osteosarcoma (83 papers, 2003 to 2025). A usually aggressive malignant bone-forming mesenchymal neoplasm, predominantly affecting adolescents and young adults. "Among these core targets, EGFR (48-sided), CASP3 (47-sided), ESR1 (42-sided), HSP90AA1 (42-sided), SRC (42-sided) and IGF1 (40-sided) have high nodes, indicating that they are closely associated with PA anti-osteosarcoma dense mechanisms." (PMID 40991530, 2025). "In the current study the diagnostic value of the IGF-1 axis to discriminate patients with osteosarcoma and Ewing sarcoma from healthy subjects was considerable; to propose this axis as a diagnostic marker, more samples need to be examined." (PMID 36713521, 2022). "The association of the IGF-1 axis with the severity of the tumor (grade and size) and tumor metastasis and recurrence indicates its possible role in the progression of osteosarcoma and Ewing sarcoma." (PMID 36713521, 2022). "IGF-1 gene polymorphisms were investigated for the association of risks and outcomes of osteosarcomas." (PMID 34069554, 2021). "Increased IGF1/IGF1R expression has been demostrated in osteosarcoma patients’ tissues and it was associated with a poor prognosis." (PMID 34440844, 2021). "In summary, available studies indicate differential expression of all IGF1 variants, depending on the type of cultured osteosarcoma cells." (PMID 32977489, 2020). "As increased dog size is strongly associated with osteosarcoma risk, IGF1 variation associated with size and fixed in all three breeds should also be considered." (PMID 30890123, 2019). "CDKN2A/B and MTMR7 contribute to osteosarcoma risk in our modeling studies, and IGF1 does so by proxy with size." (PMID 30890123, 2019). "IGF1 and other dog size genes are mentioned because large body size is a major risk factor in canine osteosarcoma." (PMID 30890123, 2019). "Taken together, our study provides new evidence that CYR61 acts as a key inducing factor in the metastatic progression of osteosarcoma by playing a critical role in primary tumor dissemination, with a process associated with IGF1/IGFR stimulation." (PMID 30642298, 2019). "Osteosarcoma and Ewing sarcoma tissues have been investigated in the context of microRNA regulation of tumor progression and metastasis, as well as regarding the cells’ response to chemotherapy, associated with components of the IGF-1 pathway(s)." (PMID 41153350, 2025). "Indeed, 7–14% of osteosarcoma cases exhibit mutations in IGF signaling genes (IGF1R, IGF1, IGF2R, and IGFBP5)." (PMID 34069554, 2021). "Meanwhile, IGF1-Ec emerges as a potential therapeutic target in osteosarcoma due to its distinct physiological role compared to IGF1." (PMID 39796756, 2025). "In this study, the authors specifically demonstrated that TAM-secreted IGF1 acts on osteosarcoma cells and up-regulates RARRES2 expression, which maintains stemness through the NF-kB pathway and promotes chemotaxis of TAMs." (PMID 38892104, 2024). "It was reported that insulin induced EMT of mammary epithelial cells, while blocking insulin-like growth factor (IGF)/insulin-like growth factor-1 factor (IGF1R) signaling axis suppressed EMT of osteosarcoma cells." (PMID 37386367, 2023). "Osteosarcoma early peak incidence occurs around early adolescence, which coincides with peak expression of circulating IGF1/IGF2." (PMID 35887382, 2022). "OncoLar is a somatostatin analogue that inhibits IGF-1 production, which can suppress the growth of osteosarcoma in vitro and metastasis in vivo." (PMID 35409176, 2022).
osteosarcoma (continued). "Early experimental studies demonstrated that human osteogenic sarcoma cells were responsive to IGF1 for mitogenesis while reduction in IGF1 levels by hypophysectomy inhibited the aggressive metastatic behavior of osteosarcoma both in vitro and in vivo." (PMID 34440844, 2021). "Beside these, Insulin-like growth factor 1 (IGF-1) is a hormone that has important function in the development and function of many tissues and it has been used as a diagnostic marker for osteosarcoma." (PMID 33757216, 2021). "We recently showed that biglycan enhances both basal and IGF-1-dependent osteosarcoma cell proliferation." (PMID 34069554, 2021). "Current knowledge on the role of miRNAs and lncRNAs on the GH/IGF1 axis and IGF system in osteosarcoma." (PMID 34484116, 2021). "Several miRNAs have been reported in the Literature to have a role in the regulation of the GH/IGF1 axis and IGF system in osteosarcoma." (PMID 34484116, 2021). "Early studies demonstrated that IGF-1 stimulates osteosarcoma cell collagen I production and that this effect was attenuated through the action of the insulin-like growth factor-binding protein-4 (IGFBP4) in a concentration-dependent manner." (PMID 34069554, 2021). "Conversely, in MG63 osteosarcoma cells or the osteoblastic cell line, biglycan mRNA expression increased with IGF-1 treatment." (PMID 33573338, 2021). "The human osteosarcoma cell line U2OS also exhibited an increase in BNIP3 expression in response to IGF-1." (PMID 31936236, 2020). "Our RT-PCR results showed that IL-10, TGF-β1, VEGFA, and IGF-1 were significantly increased in osteosarcoma tissues." (PMID 32908942, 2020). "In the case of CC and HCC, a role of oncogenic viruses (HPV, HCV) is suggested, while in other cancers there is a possibility of hormonal influence (testosterone), e.g., IGF1 splicing process in osteosarcoma." (PMID 32977489, 2020). "In osteosarcoma, the expression of different IGF1 isoforms (mRNA, protein) is only reported in in vitro model based studies." (PMID 32977489, 2020). "In fact, the IGF-1 signaling pathway is activated in osteosarcoma promoting proliferation and chemotherapy resistance by activating the AKT signaling pathway." (PMID 30881341, 2019). "The silencing of CYR61 or the blockade of IGF1/IGF1Rβ pathway significantly reduced the pro-metastatic activity of osteosarcoma cells, as demonstrated in vitro or in preclinical models." (PMID 30642298, 2019). "Some worrisome data for patients harboring osteosarcoma regard the interaction of IGF-1 signaling and osteosarcoma suggesting that supplementation of osteosarcoma cell lines with IGF-1 increases their growth." (PMID 30881341, 2019). "The IGF1 3′UTR functions as a ceRNA to promote angiogenesis by sponging the miR-29 family in osteosarcoma." (PMID 28427228, 2017). "The result showed that IGF-1 expression was increased in osteosarcoma relative to the paired bone tissues." (PMID 27468358, 2015). "In this study, we found that IGF-1 serves as a downstream mediator of tumor suppressor function in osteosarcoma." (PMID 27468358, 2015). "The effect of IGF-1 stimulation on PRKCε protein in highly metastatic osteosarcoma cells was investigated." (PMID 24216982, 2013). "Highly metastatic M112 osteosarcoma cells were serum starved for at least 24 h, followed by the addition of either fresh serum-free media or media containing 50 ng/mL IGF-1." (PMID 24216982, 2013). "Osteosarcoma cell lines are dependent on IGF-1 via IGF-1R for in vitro growth, and IGF-1R expression has been associated with poor prognosis." (PMID 23383402, 2013). "Preclinical work has suggested a role of insulin-like growth factor-1 (IGF-1) in the proliferation of osteosarcoma cells in vivo." (PMID 22587902, 2012).
osteosarcoma (continued). "Osteosarcoma incidence is highest during puberty when endogenous sex hormones, growth hormones, and insulin-like growth factor 1(IGF1) levels are at their highest, so this biological pathway is likely to play an important role in osteosarcoma etiology." (PMID 21437228, 2011). "The insulin-like growth factor signaling system is important in the formation and homeostasis of bone, and differential expression of IGF1 has been observed in osteosarcomas." (PMID 21619704, 2011). "The peak incidence of osteosarcoma occurs during adolescence, corresponding to both the growth spurt and peak concentrations of circulating GH and IGF-1." (PMID 21197468, 2011). "In different human osteosarcoma cell lines an inhibition of the IGF-1- and -2-stimulated uptake of thymidine as well as a partial inhibition of the basal DNA synthesis was observed when the IGF-1R was blocked by monoclonal antibody α-IR3." (PMID 12618883, 2003). "Compared to the sham group, the SNL group had higher gene expression levels of Gadd45g (growth arrest and DNA-damage-inducible 45 gamma) and Fos (FBJ osteosarcoma oncogene), while it had lower gene expression levels of Igf1, Ccl2, Hdac2, Rtn4rl1, Nfkb2, Gpr84, Pik3cg, and Abcc8." (PMID 38790607, 2024). "To determine the impact of Lnc-CLSTN2-1:1 on the cell cycle via the PI3K/AKT pathway, which contributes to the malignant biological behavior of osteosarcoma, we pretreated cells with igf-1 (PI3K /Akt agonist) and then measured the protein levels of P-AKT and cyclinD1." (PMID 38356713, 2024). "Interestingly, IGF-1 stimulates collagen-1 production in osteosarcoma cells that can further arrange cells, shape, behavior, and proliferation." (PMID 36713521, 2022). "In summary, our data suggested that IGF-1R, IGF-1, IGFBP-1, and IGFBP-3 levels are associated with bone tumor malignancy, metastasis, and recurrence that might serve as biomarkers for osteosarcoma and Ewing sarcoma recurrence." (PMID 36713521, 2022). "Comparing the osteosarcoma, Ewing sarcoma, and GCT groups, the over-expression of the IGF-1 axis was more prominent in osteosarcoma and Ewing sarcoma compared to GCT which might be influenced by higher tumor grades and disease stages in these groups." (PMID 36713521, 2022). "Interestingly, a correlation between IGF-1 signaling and PG synthesis was identified in osteosarcoma." (PMID 34069554, 2021). "There is evidence that IGF-1 related pathways are involved in osteosarcoma progression." (PMID 32742448, 2020). "In osteosarcoma, IGF1 3ʹUTR promotes angiogenesis by sponging miR-29 family." (PMID 32066878, 2020). "This suggests that CYR61 may represent a potential pivotal target for therapeutic management of metastases spreading in osteosarcoma, in correlation with IGF1/IGFR pathway." (PMID 30642298, 2019). "In osteosarcoma, increased levels of IGF-1 and IGF-1R have been found that seem to lead to tumor progression through transformation, proliferation, decreased susceptibility to apoptosis, and a phenotype prone to metastasis, including increase cell motility, invasion, and angiogenesis." (PMID 30881341, 2019). "Thus CDKN2A/B, IGF1 and the two single candidates at their loci – MTMR7, FGF9 – seem likely to be associated with canine osteosarcoma risk." (PMID 30890123, 2019). "Control and CYR61-modified osteosarcoma cells were tested for IGF1 expression levels." (PMID 30642298, 2019). "Osteosarcoma is a malignant bone tumour with an incidence peak coinciding with the adolescent growth spurt, a time when the hormonal milieu is characterized by high GH, IGF1 and insulin levels." (PMID 28316059, 2017). "Moreover, there was an inverse correlation between miR-26a expression and IGF-1 expression in osteosarcoma tissues." (PMID 27468358, 2015). "Furthermore, miR-26a inhibitors transfection increased its mRNA and protein levels, further indicating that IGF-1 is a target of miR-26a in osteosarcoma cells." (PMID 27468358, 2015).
osteosarcoma (continued). "Taken together, the current study provided novel evidence that miR-26a is significantly downregulated in osteosarcoma clinical specimens and appears to function as a tumor suppressor in osteosarcoma through the regulation of IGF-1 expression and cell proliferation." (PMID 27468358, 2015). "Finally, we examined IGF1 expression in n=32 pairs of osteosarcoma and matched adjacent tissues by qRT-PCR." (PMID 27468358, 2015). "Since susceptible large breed dogs have higher IGF-1 levels, and IGF-1R is often overexpressed in canine osteosarcomas, a link between IGF-1 signaling and osteosarcoma has been proposed." (PMID 22833734, 2012). "This epidemiological correlation has led to the hypothesis that high levels of IGF-1 play an important role in the pathogenesis of osteosarcoma." (PMID 21197468, 2011). "Thus, miR-26a could be described as a tumor-suppressive miRNA in osteosarcoma and, interestingly, IGF1 was shown to be a direct target of miR-26a." (PMID 34484116, 2021). "Osteosarcoma mouse models exhibit reduction in metastatic disease and an 85% reduction in IGF-1 levels following removal of the pituitary gland, which suggests that IGF-1, as a downstream effector of growth hormone (GH), may be partially responsible for osteosarcoma proliferation." (PMID 32961800, 2020). "miR-26a could also inhibit the proliferative abilities of osteosarcoma by targeting IGF-1." (PMID 29113367, 2017). "Similar results have been recently obtained in osteosarcoma, in which coculture experiments with TAMs and osteosarcoma cells indicate a critical role of TAM-produced IGF1 in osteosarcoma stemness." (PMID 38892104, 2024). "Human alveolar bone marrow stem cells exposed to PRF extracts showed a high expression of IGF-1, similar to MG63 osteosarcoma cells and primary osteoblasts." (PMID 37888168, 2023). "The circulating level of IGF-1, IGFPB-1, and IGFBP-3 were increased in osteosarcoma and Ewing sarcoma and GCT groups that were correlated significantly to the tumor severity." (PMID 36713521, 2022). "IGFBP-3, an essential regulator of IGF-1 signaling, was shown to facilitate VCAM-1 expression that promoted human osteosarcoma cell migration capacity through the PI3K, Akt, and AP-1 signaling pathways." (PMID 34069554, 2021). "IGF-1 and IGF-1R push osteosarcoma progression through subsequent malignant transformation, proliferation, attenuated susceptibility to apoptosis, and the differentiation of a prone to metastasis phenotype." (PMID 34069554, 2021). "IGF-1 treatment was shown to stimulate XTI and alkaline phosphatase expression in Saos 2 cells indicating its crucial role in osteosarcoma cell PG synthesis." (PMID 34069554, 2021). "Osteoclast activity leads to bone degradation and the release of protumor factors, such as insulin-like growth factor 1 (IGF1) or transforming growth factor-β (TGF-β), which enhance osteosarcoma cell proliferation." (PMID 34204674, 2021). "Increased expression of IGF-1 and IGF-1R have been reported in the majority of sarcomas, including osteosarcoma, EWS, and soft tissue sarcomas, and has been correlated with disease progression." (PMID 34069554, 2021). "IGFBP5 primarily binds to insulin growth factors to inhibit the IGF1 and IGF2 signalling pathways, thereby inhibiting the proliferation, migration and invasion of osteosarcoma, and is a key inhibitor of in situ osteosarcoma growth and lung metastasis." (PMID 33614075, 2021). "Expression of IGF receptor 1 (IGF1R), IGF-1, and IGF-2 have been reported in osteosarcoma cell lines and patient samples, further suggesting its role in osteosarcoma pathogenesis." (PMID 32961800, 2020). "Luteolin’s antiproliferative activity resides in the potential to induce cell cycle arrest via inhibiting IGF-1-mediated PI3K/PKB activation, and ferulic acid has been proven effective in inhibiting proliferation of osteosarcoma cells." (PMID 31024305, 2019).